CLDN1 (claudin 1)
Diseases named in the same sentence as CLDN1 in open-access papers (continued):
Sharing a sentence is not in itself a finding about the gene and the disease.
cancer (continued). "CLDN1 expression is predictive and prognostic in colorectal and other cancers." (PMID 26894861, 2016). "Claudin 1 has been clearly demonstrated to directly promote carcinogenesis in some cancers." (PMID 27649506, 2016). "The mislocalization of claudin 1 to the cytoplasm, has been observed in several cancers." (PMID 26633531, 2015). "Claudin 1 involvement in EMT has also been well documented in several cancers." (PMID 26633531, 2015). "Among these genes, HMGA2, CLDN1, TFPI2, KIAA0101 and EGR1 are cancer related genes according to Diseases Association Analysis and increased expression of EGR1 was confirmed by further semi-quantitative RT-PCR, quantitative RT-PCR and western blot in BCL6B re-expressed HepG2 and SNU449 cells." (PMID 25909168, 2015). "Interestingly, aberrant expression of claudin 1 has been observed not only in different cancers but in different histological subtypes of the same cancer." (PMID 26633531, 2015). "In summary, the role of CLDN1 in cancer progression and prognosis is far from clear." (PMID 24321518, 2013). "Recent studies have shown that the expression of certain claudins especially claudin-1 and claudin-4 increases during metastasis and genetic inhibition of their expression has profound effect on the metastatic abilities of cancer cells though in a tissue specific fashion." (PMID 23591077, 2013). "Interestingly, its inhibitory functions are in contrast to findings for another member of the TJ family, Claudin 1, which has been shown to promote cancer growth and metastatic properties." (PMID 21468049, 2011). "Some of the tight junction proteins including Claudin-1 and Claudin-4 are upregulated in several cancers." (PMID 18781153, 2008). "Specifically, CLDN1,3,4,5,7,10,16 have been found altered in various cancers." (PMID 16836752, 2006). "CLDN1 is typically downregulated in various cancers, but has also been reported to be elevated." (PMID 16836752, 2006). "Moreover, sequentially combining oxaliplatin with an anti-CLDN1-ADC could be beneficial for patients with chemotherapy-resistant cancer." (PMID 39065798, 2024). "In addition, the researchers suggested that asiatic acid may play a role in inhibiting migration due to reduced expression of the mesenchymal markers N-cadherin, β-catenin, claudin-1, and vimentin, which are key in cancer cell migration and metastasis." (PMID 38610995, 2024). "However, claudin-1 has also been found to participate in cancer cell migration through activation of focal adhesion kinase (FAK), another nonreceptor protein tyrosine kinase that controls fundamental cellular processes, including migration under physiological or disease conditions." (PMID 34354941, 2021). "Therefore, when cancer cells induce disruption of the junctions between endothelial cells, claudin-1 is exposed to the circulation; transmigration of cancer cell-expressed claudin-1 can be inhibited by homotypic claudin-1 interaction, which suppresses brain metastasis." (PMID 34354941, 2021). "Moreover, to evaluate whether cisplatin-resistance cells showed low CLDN1 expression, we got the cisplatin-resistant A549 cells by treating cancer cells with slowly increased the concentration of cisplatin for six months." (PMID 32754286, 2020). "The regulatory mechanism of CLDN1 expression may differ according to the type of carcinoma." (PMID 31551535, 2019). "However, the significance of claudin-1 expression in cancer cells is not well understood." (PMID 20937153, 2010). "In particular, EphB4, CLDN1, and LAT1 are expressed at high frequencies in most cancers, with a few exceptions." (PMID 40076777, 2025). "CLDN1, EphB4, LAT1, FOXM1, HSP105α, ROBO1, and SPARC were identified as potential targets for common cancer antigens for primary CRC." (PMID 40806530, 2025). "Representative examples of five common cancer antigens, GPC3, ROBO1, CLDN1, EphB4, and LAT1, expressed on the cell membrane of cancer cells are shown." (PMID 40076777, 2025).
cancer (continued). "A detailed analysis of the changes in the transcriptome profile of CLDN1-inhibited GIST and its potential impact on the behavior of cancer cells, including their sensitivity to chemotherapy, is described in more detail in the Discussion section." (PMID 40943068, 2025). "CLDN1, EphB4, LAT1, HSP105α, and ROBO1 expression slightly decreased or remained unchanged but remained consistently high across both cancer types." (PMID 40806530, 2025). "Subsequently, claudin-1 activates the c-Abl-Ras-Raf-1-ERK1/2 pathway, which mediates epithelial–mesenchymal transition and, eventually, cancer." (PMID 37627123, 2023). "We constructed a multi-cancer fibroblast atlas, in which fibroblasts were classified into six clusters: BAMBI+ FBs, CLDN1+ FBs, COL11A1+ FBs, CXCL14+ FBs, DPT+ FBs and RGS5+ FBs." (PMID 36744260, 2023). "As such, both CLDN1 and LCN2 have been suggested to be involved in cancer dedifferentiation, future work is needed to establish the mechanistic basis of their actions—especially in the context of obese environments." (PMID 35013251, 2022). "The expression of CLIC2 and tight junction proteins is upregulated in non-cancer, compared with cancer cells, and CLIC2 regulates the formation of tight junction proteins such as claudin 1, claudin 5, zonula occludens-1, and occludin." (PMID 35205604, 2022). "We found that the mRNA expression of IL7R, COL22A1, ZNF185, and SRD5A2 were upregulated in cancer tissues, while PTGS2 and CLDN1 were higher in normal tissues, consistent with our previous analysis." (PMID 35813821, 2022). "Another identified miR-29a target CLDN1 is a tight junction protein that facilitates cell-ECM communication and EMT in various cancer types." (PMID 32660466, 2020). "Functional experiments showed that miR-514b-5p triggers EMT and invasion of cancer cells via targeting cadherin 1 (CDH1, also named E-cadherin 1) and claudin 1 (CLDN1)." (PMID 33066509, 2020). "Another explanation is that both CLDN1 and CLDN11 induce chemoresistant characteristics of cancer cells." (PMID 31551535, 2019). "Genetic knockdown of EHMT2, a histone methyltransferase, reduces cancer cell migration and invasion by regulating the expression of EMT-related markers (E-cadherin, claudin-1, and vimentin)." (PMID 31717460, 2019). "When CLDN1, CLDN4, and CLDN18 were analyzed, as single markers, across 18 cancer tissue types, the AUC values were 0.756 (p=1.4×10-4), 0.647 (p=0.156), and 0.792 (p=2.5×10-4), respectively." (PMID 29050243, 2017). "When CLDN1, CLDN4, and CLDN18 were analyzed throughout the 18 cancer types as a multi-marker set, the AUC value was 0.850 (p=3.3×10-4)." (PMID 29050243, 2017). "The percentage of the counted cancer cells with 3-4 copies per cell of TERC was more than 90%, and the percentage of the counted cancer cells with 3-4 copies per cell of CLDN1 was more than 80%." (PMID 27974683, 2016). "Claudin-1 (CLDN1) is involved in the formation of tight junctions which are altered in colorectal and other cancers." (PMID 26894861, 2016). "To elucidate the role of CLDN1 in gastric carcinogenesis, we constitutively knocked down CLDN1 expression in the human cancer cells BGC-823 and HS-746T using shRNA (BGC-823/CLDN1-KD and HS-746T/CLDN1-KD)." (PMID 25544763, 2015). "Thus, loss of CLDN1 may lead to lack of intercellular cohesion between cancer cells, promote invasiveness, and contribute to lymph node metastasis." (PMID 25393310, 2014). "Genes that were upregulated by demethylation but not methylated included genes that have been described previously as TSGs in other cancer types (e.g. BAP1, IGSF4, RRM2 (Gautam and Bepler (2006)), PMAIP1, claudin-1; and ICAM1;)." (PMID 18195710, 2008). "CLDN1, EphB4, and LAT1 were expressed only on the cell membrane of cancer cells." (PMID 40076777, 2025).
cancer (continued). "On the other hand, it has been revealed that three antigens—EphB4, CLDN1, and LAT1—are frequently expressed only on the cell membrane of cancer cells in various solid cancers, suggesting that they may be ideal targets for CAR-T cell therapy." (PMID 40076777, 2025). "In cancer cells, BKV-B1-miR-5p promotes cell motility and invasiveness by directly targeting CLDN1." (PMID 38245774, 2024). "Monoclonal antibodies targeting CLDNs, particularly CLDN1 and CLDN4, hold promise as therapeutic agents in the treatment of various cancers, with potential synergistic effects when combined with known anti-cancer agents like 5-fluorouracil and anti-EGFR antibodies." (PMID 38731853, 2024). "Downregulation of claudin-1 with various strategies, including PKC inhibition, C. perfringens enterotoxin, RET inhibition, or exogenic delivery of anti-cancer miRNA, may be beneficial in the case of PTC, FTC, and MTC." (PMID 39458944, 2024). "With respect to the genes having interaction(s) with miRNAs, we realized four down-regulated vDEGs (TMEM100, MYH11, CHRDL1, and FAM107A) to the accompaniment of five up-regulated vDEGs (KLK10, CLDN1, SLC6A6, MMP11, and SLC7A5) being documented by the GEPIA in both COAD and READ cancer types." (PMID 35333898, 2022). "Additionally GH assists cell motility and invasion, as well as, acquiring cancer stem cell-like criteria of HCC cells, by inhibiting another tight junction protein called Claudin-1 through activation of STAT3 in HCC." (PMID 36374927, 2022). "Reports documenting that SRGN promotes cancer cell aggressiveness and metastasis through several signaling pathways, including CD44/NF-κB/CLDN1 axis, HIF-1α/SRGN axis, and SRGN/TGFβ2 axis, may further support our observations presented here." (PMID 34059749, 2021). "Recent studies also associate it with epithelial to mesenchymal transition (EMT), a biological phenomenon involved in the early progression of cancer metastasis, and the modulation of EMT regulators like Vimentin, Claudin-1 and other transcription factors, playing a dual role in EMT." (PMID 34440232, 2021). "In agreement with previous studies, we showed that ERK–ZEB1 signaling promotes epithelial to mesenchymal transition in cancer cells, and treatment of CD44-overexpressing cells with ERK phosphorylation inhibitor PD98059 reversed ZEB1 and Claudin-1 expression levels." (PMID 34439211, 2021). "High expression of CLDN-1 was reported in intestinal type gastric cancer that correlated with lymph node metastasis, advanced TNM (classification of malignant tumors) stage, recruitment, and activation of MMP-2 and MMP-9, which are all responsible for enhanced cell invasion and metastasis." (PMID 31952355, 2020). "One study established that overexpression of CLDN-1 induces MMP-2 in SNU-354, -423 and -449 HCC cells resulting in increased invasion and migration of the cancer cells compared to the normal liver cells and other CLDN-1 expressing HCC cells such as SNU-398 and SNU-475." (PMID 31952355, 2020). "The copy numbers of TERC and CLDN1 in cancer tissues were both increased significantly compared with normal cervical tissue." (PMID 27974683, 2016). "Membrane proteins, such as CLDN1, EphB4, and LAT1, were highly expressed in primary CRC and liver metastases, suggesting that CAR-T cell therapy targeting these three cancer antigens could be a viable option, particularly in 30% of cases with reduced HLA class I expression on cancer cell membranes." (PMID 40806530, 2025). "On the other hand, a claudin 1-based antibody drug conjugate may be more appropriate for use in CMS2 colon cancers, which express higher levels of the target, thus helping to direct the cytotoxic moiety to the cancer cells." (PMID 37998722, 2023).
cancer (continued). "EMT is a crucially phenotypic plasticity process for migratory and invasive properties in cancer, blocking of TRIM37 significantly resulted the downregulation of mesenchymal cell markers of N-cadherin and Vimentin, as well as the upregulation of epithelial marker Claudin-1." (PMID 34130705, 2021). "Based on the complexity of the topic, there is no one statement we can make for CLDN-1 role in cancer or barrier function since it is more intricate (Claudins are upregulated or downregulated in cancer and may or may not play a role in barrier function)." (PMID 31952355, 2020). "Claudin 1 knockdown also resulted in a significant up regulation of the expression of EMT related genes, SERPINE 1 (plasminogen activator inhibitor type 1, PAI1) and secreted phosphoprotein 1 (SSP1; also known as osteopontin) that have been shown to suppress cancer cell migration." (PMID 23721519, 2013). "Notably, no genetic alteration has been identified in CLDN1 in cancer." (PMID 32754286, 2020).
infection (144 papers, 2008 to 2026). The state of being infected such as from the introduction of a foreign agent such as serum, vaccine, antigenic substance or organism. "The MZ group exhibited a significant downregulation in tight junction-associated protein expression, such as claudin-1, occludin, and ZO-1, which suggests that the infection weakens the intestinal epithelial barrier’s structural integrity." (PMID 41060041, 2025). "Infection with Aa and/or Sg induced changes in the transcriptional profile of genes encoding TJ proteins claudin 1, claudin 2, and occludin and the anchoring protein zonulin in the intestinal barrier." (PMID 39125663, 2024). "Epithelial tight junction protein gene expression analysis revealed a significant upregulation of CLDN1 with the infection and microbiota, indicating a potential loss of the intestinal barrier integrity." (PMID 37680750, 2023). "Treatment of keratinocytes with this peptide resulted in decreased TEER, altered expression and/or localization of tight junction-related proteins (claudin-1 and occludin), and increased susceptibility to infection with VV." (PMID 37737609, 2023). "Owing to the viral genomic mutations, HCV-JFH1-tau Lot B1 should acquire the CLDN1-independent infection (entry) phenotype." (PMID 36424447, 2022). "Next, to identify mutation sites involved in the CLDN1-independent infection by HCV-JFH1-tau Lot B1, we tested the infectivity of HCVee having Lot B1-type envelope proteins with each wild-type point mutation." (PMID 36424447, 2022). "Conversely, introducing a single M706L point mutation into HCV-JFH1 leads to acquiring a CLDN1-independent infection phenotype." (PMID 36424447, 2022). "Altogether we concluded that M706L mutation in HCV-JFH1 is essential for its CLDN1-independent infection phenotype." (PMID 36424447, 2022). "The upregulation of claudin-1 mRNA expression by the infection with LT2 probably prevented the loss of electrolytes that occurs in diarrhea." (PMID 33670419, 2021). "Claudin-1 protein expression levels seemed to slightly diminish at late times post-infection in the TLR3-deficient OE cells, and its cellular distribution remained mostly cytoplasmic throughout infection." (PMID 30625140, 2019). "Occludin, Claudin -1 and β-catenin are tight junction protein which gets manipulated during pathogenic infection and blood-brain barrier breaching." (PMID 30001342, 2018). "The results of the present study indicate that cell infection with P. gingivalis promoted the expression of the TJ genes encoding occludin, claudin-1 and claudin-4, which enhances barrier function and decreases cell-cell permeability." (PMID 29319048, 2018). "After 24 h post-infection with C. jejuni (intracellular survival), the expression of 29 genes was up-regulated in HT-29 treated cells with EcN, while one gene encoding CLDN1 was down-regulated." (PMID 28878749, 2017). "At the same time, because the susceptibility of cells to infection increased with CLDN1 expression, infected cells tended to have higher CLDN1 expression on average than uninfected cells." (PMID 22545157, 2012). "The introduction of M32I or K48E into claudin-7 rendered 293T cells partially permissive to HCVpp infection, but the combination of both mutations supported HCVpp entry as efficiently as claudin-1." (PMID 19643019, 2009). "In addition, the reduction of Claudin-1 in epithelial cell membranes caused by pathogens’ adhesion contributes to epithelial barrier damage and infection." (PMID 36228044, 2022). "Moreover, we observed that infection of endothelial cells (HUVECs) results in loss of claudin-1 and JAM-1 proteins." (PMID 22655077, 2012). "Here, we showed that the different susceptibilities to infection of cells expressing different levels of CLDN1 and the ensuing viral kinetics may render these conflicting observations two sides of the same coin." (PMID 22545157, 2012). "This followed from the higher susceptibility to infection of cells expressing more CLDN1." (PMID 22545157, 2012).